USP48 (ubiquitin specific peptidase 48)
Description:
Deubiquitinase that recognizes and hydrolyzes the peptide bond at the C-terminal Gly of ubiquitin. Involved in the processing of polyubiquitin precursors as well as that of ubiquitinated proteins. Plays a role in the regulation of NF-kappa-B activation by TNF receptor superfamily via its interactions with RELA and TRAF2. May also play a regulatory role at postsynaptic sites. Plays an important role in cell cycle progression by deubiquitinating Aurora B/AURKB and thereby extending its stability. In the context of H.pylori infection, stabilizes nuclear RELA through deubiquitination, thereby promoting the transcriptional activity of RELA to prolong TNFAIP3 de novo synthesis. Consequently, TNFAIP3 suppresses caspase activity and apoptotic cell death. Also functions in the modulation of the ciliary and synaptic transport as well as cytoskeleton organization, which are key for photoreceptor function and homeostasis. To achieve this, stabilizes the levels of the retinal degeneration-associated proteins ARL3 and UNC119 using distinct mechanisms. Plays a positive role in pyroptosis by stabilizing gasdermin E/GSDME through removal of its 'Lys-48'-linked ubiquitination.
Synonyms: USP31; FLJ23277; FLJ11328; FLJ20103; FLJ23054; MGC14879; DFNA85; RAP1GA1
Tractability: PROTAC: ubiquitination databases record sites on it; its protein half-life has been measured.
Gene: Protein-coding gene on chromosome 1 (21,678,298 to 21,783,606, reverse strand). Ensembl gene ENSG00000090686.
Subcellular location: Cytoplasm; Nucleus; Cell projection, cilium
Subcellular location (Human Protein Atlas): Nucleoplasm; Cytosol; Mitochondria
Pathways (Reactome):
Metabolism of proteins: Ub-specific processing proteases
Gene Ontology:
Molecular function: cysteine-type deubiquitinase activity; deubiquitinase activity; protein binding; cysteine-type endopeptidase activity
Biological process: protein deubiquitination
Cellular component: cytosol; mitochondrion; nucleoplasm; nucleus; cilium; cytoplasm
Genetic constraint (gnomAD): Loss-of-function variants: 37 observed, 130.63 expected, observed/expected ratio (o/e) 0.28, 90% interval 0.22 to 0.37. The upper end of that interval is the gene's LOEUF score, 0.37, which puts it in group 1 of 6, group 1 being the genes least tolerant of losing a copy. Missense variants: 778 observed, 1,201.3 expected, observed/expected ratio (o/e) 0.65, 90% interval 0.61 to 0.69. Synonymous variants: 379 observed, 413.36 expected, observed/expected ratio (o/e) 0.92, 90% interval 0.84 to 1.
Homologues: Orthologues: chimpanzee USP48 (99% identical), pig USP48 (99% identical), dog USP48 (98% identical), rabbit USP48 (98% identical), rat Usp48 (95% identical), mouse Usp48 (95% identical), macaque USP48 (93% identical), guinea pig USP48 (92% identical), tropical clawed frog usp48 (77% identical), zebrafish usp48 (70% identical). Paralogues in human: USP7 (21% identical), USP24 (14% identical), USP31 (14% identical), USP9X (14% identical), USP34 (14% identical), USP42 (14% identical), USP9Y (14% identical), USP36 (14% identical), USP47 (13% identical), USP25 (12% identical), USP28 (12% identical), USP40 (12% identical), and 59 more.
Diseases named in the same sentence as USP48 in open-access papers:
USP48 is named in the same sentence as 35 diseases in open-access papers, as found by Europe PMC text mining. Sharing a sentence is not in itself a finding about the gene and the disease. The quoted sentences say what the papers report.
corticotroph adenomas (9 papers, 2018 to 2025). "A small number of non-USP8-driven corticotropinomas are due to somatic hotspot variants in USP48 or BRAF; the latter is a well-known mutational hotspot in cancer." (PMID 38067388, 2023). "Hyperactive mutations of Usp8 and Usp48 cause excessive ACTH secretion from corticotroph adenomas, implying that USP8 and 48 have the potential to modulate the hypothalamus-pituitary-adrenal axis under physiological conditions." (PMID 36834633, 2023). "Almost 13% of ACTHomas cases have been shown to harbor specific p.Met415 mutations within the catalytic domain of USP48, indicating a functional relevance of this ubiquitin-specific protease." (PMID 33266265, 2020). "Recently, USP48 and BRAF have been reported as additional target genes, with somatic variants of BRAF gene in 16% of patients and of USP48 gene in 23% of USP8-negative corticotropinomas." (PMID 31877737, 2019). "We assumed that mutations in BRAF and USP48 should be involved in the pathogenesis of corticotroph adenomas." (PMID 30093687, 2018). "In summary, our study identified frequent BRAF and USP48 mutations in corticotroph adenomas carrying wild-type USP8 and indicated that these mutations cause Cushing’s disease mainly by activating POMC gene transcription and increasing plasma ACTH levels." (PMID 30093687, 2018). "Moreover, the higher mRNA abundance of POMC in AtT-20 cells stably transfected with USP48 M415I/V, further supports the notion that the M415I/V substitution causes corticotroph adenomas by up-regulating POMC transcription." (PMID 30093687, 2018). "The mutational status of BRAF, USP8, and USP48 in corticotroph adenomas may be used in the future to characterize the molecular subtypes and guide targeted molecular therapy." (PMID 30093687, 2018). "Therefore, similar to USP8, BRAF and USP48 mutations appear to be unique genetic signatures of corticotroph adenomas." (PMID 30093687, 2018). "Furthermore, recently identified somatic mutations in the deubiquitinases USP8 and USP48 occurs with greater frequency in women than men with Cushing’s disease, suggesting that the corticotrope adenoma itself may harbour features which contribute to gender-dependent differences in Cushing’s disease." (PMID 32183012, 2020). "Missense mutations of USP48, including M415I/V substitutions, were also identified as most frequent mutations in USP8 wild-type corticotroph adenomas." (PMID 30093687, 2018). "In this study the authors report USP48 and BRAF are frequently mutated in USP8 wild-type corticotroph adenomas, and cause Cushing’s disease mainly through promoting the promoter activity of POMC." (PMID 30093687, 2018). "We next examined the prevalence of USP48 and BRAF mutations in additional corticotroph adenomas with wild-type USP8 by targeted sequencing." (PMID 30093687, 2018). "Exosome sequencing of 18 USP8 non-mutated corticotroph adenomas (Cushing disease, n = 15; Nelson’s tumors, n = 3) indicated that the prevalence of USP48 mutations was 17% (3 samples)." (PMID 36834633, 2023). "Corticotropinomas carrying USP48 hotspot defects were significantly smaller in one study and displayed a higher rate of cavernous sinus invasion in a different cohort, compared with USP48 wild-type tumors." (PMID 38067388, 2023). "Somatic BRAF V600E mutation has been reported in several tumors; in 2018, such a mutation was detected in 16.5% of a case series of USP8-WT corticotrope adenomas; this alteration was not mutually exclusive with USP48 mutations." (PMID 35743266, 2022). "Immunohistochemistry also proved that USP48-mutated corticotroph adenomas were negative or weakly positive for the phosphorylation of these molecules." (PMID 30093687, 2018). "Immunohistochemical analysis of USP48 protein in a series of corticotroph adenomas revealed that there was no degradation or enhanced expression of USP48 in USP48-mutated tumors compared to tumors with wild-type USP48." (PMID 30093687, 2018).
adenoma (5 papers, 2018 to 2022). A neoplasm arising from the epithelium. "Here, we performed further exome sequencing and identified recurrently-mutated genes including BRAF and USP48 in USP8 wild-type corticotroph adenomas." (PMID 30093687, 2018). "These modifications constitutively increase the deubiquitinase activity of USP48, leading to the formation of corticotrope adenomas and ACTH hypersecretion." (PMID 35743266, 2022). "None of the CD-causing ACTH-secreting adenomas showed the previously reported SNV in the genes encoding USP48, BRAF, BRG1 and CABLES1." (PMID 35563252, 2022). "Strikingly, none of the samples, including 20 growth hormone-secreting, 20 prolactin-secreting, and 20 non-functioning adenomas, carried either USP48 or BRAF mutations." (PMID 30093687, 2018). "With the recognition of the importance of USP8 mutations, another two mutated genes in the mitogen-activated protein kinase (MAPK) pathway, USP48 and BRAF, have also been detected in corticotropin-secreting adenomas." (PMID 33574795, 2020).
glioblastoma (5 papers, 2020 to 2025). The most malignant astrocytic tumor (WHO grade IV). "In human glioblastoma, there exists a positive correlation between the expression levels of USP48 and Gli1." (PMID 40034124, 2025). "Among the members of DUB family, USP48 has been reported to regulate glioblastoma, lung cancer, as well as head and neck squamous carcinoma." (PMID 35413838, 2022). "Of note, USP48 and GLI1 expression levels directly correlate in human glioblastoma specimens, and they are linked to tumor malignancy grade." (PMID 32531973, 2020). "Zhou and co-authors recently highlighted the USP48 involvement in HH signaling regulation and its role as promoter of glioblastoma cell proliferation and tumorigenesis." (PMID 32531973, 2020). "In support for a cause-effect relationship between GLI inhibition and the reduction in USP48 and iASSP mRNA levels, USP48 was found to be a direct transcriptional target of GLI1 in glioblastoma cells, and iASPP to be induced by GLI1/2 activation via E2F1 in melanoma cells." (PMID 35251038, 2022). "In human glioblastoma, USP48 and Gli1 expression levels were positively correlated, and high USP48 expression levels correlated with higher grades of glioma malignancy, suggesting that the USP48-Gli1 regulatory axis is critical for glioma cell proliferation and glioblastoma tumorigenesis." (PMID 34948134, 2021).
glioma (3 papers, 2020 to 2025). A benign or malignant brain and spinal cord tumor that arises from glial cells (astrocytes, oligodendrocytes, ependymal cells). "Moreover, high expression levels of USP48 are associated with a higher degree of malignancy in gliomas." (PMID 40034124, 2025). "The intriguing finding is that Gli1 transcriptionally activates USP48 in glioma cells, thereby establishing a positive feedback loop that governs Hh signaling." (PMID 40034124, 2025). "In addition to USP7 and OTUB2, the deubiquitinase USP48 was found to activate Hh signaling by stabilizing Gli1 protein in glioma cells." (PMID 34948134, 2021). "Interestingly, USP48 is transcriptionally activated by Gli1 in glioma cells, thus forms a positive feedback loop to regulate Hh signaling." (PMID 34948134, 2021). "The specific function of USP48 on GLI1 promotes the proliferation and the colony formation of glioma cells in vitro." (PMID 32531973, 2020).
hepatocellular carcinoma (3 papers, 2023 to 2024). A malignant tumor that arises from hepatocytes. "Similarly, USP48, primarily localized to the nucleus, impedes metabolic reprogramming to inhibit hepatocellular carcinoma development by removing K48-linked ubiquitination at the K33 and K128 sites of SIRT6 to stabilize SIRT6." (PMID 38245760, 2024). "This is because the ubiquitin-specific peptidase 48 (USP48) in hepatoma cells can combine with SIRT6, a histone deacetylase, to improve the stability of SIRT6, which plays a role in weakening the glycolysis of hepatoma cells." (PMID 37582735, 2023). "It has been demonstrated that methyltransferase-like 14-induced m6A modification participates in the regulation of USP48 in hepatocellular carcinoma by maintaining Usp48 mRNA stability." (PMID 37205094, 2023).
liver cancer (3 papers, 2022 to 2025). An epithelial or non-epithelial malignant neoplasm that arises from the liver. "In human liver cancer, the expression of USP48 is downregulated, reducing the stability of SIRT6, which induces the occurrence of liver cancer." (PMID 36578520, 2022). "In liver cancer, multiple different groups’ investigations showed that METTL14 inhibits EMT, invasion and metastasis of liver cancer cells by regulating m6A-modified target mRNAs such as EGFR/PI3K/AKT, DGCR8/primiR-126, USP48/SIRT6/glycolysis, CSAD, GOT2 and SOCS2." (PMID 40734692, 2025).
ciliopathies (2 papers, 2022 to 2024). "Additional work is needed to shed light on the role of USP48 in the retina, but our results posit it as a new candidate/modifier gene for unsolved ciliopathies and inherited retinal dystrophies." (PMID 36293380, 2022). "Primarily localized in the nucleus, USP48 plays a crucial regulatory role in inherited retinal dystrophy (IRD) and ciliopathies by removing the ubiquitination of ARL3 and stabilizing UNC119a." (PMID 38245760, 2024).
inherited retinal dystrophy (2 papers, 2022 to 2024). An instance of retinal degeneration that is caused by an inherited modification of the individual's genome. "We propose USP48 as a potential candidate gene for unsolved inherited retinal dystrophies." (PMID 36293380, 2022).
lung carcinoma (2 papers, 2017 to 2022). "To determine whether USP48, through its ability to regulate NF-κB transcription factor, could play a role in the regulation of Mdm2 expression, we induced an siRNA-mediated knockdown of USP48 in human osteosarcoma U2OS cells and human lung carcinoma H1299 cells." (PMID 28233861, 2017).
melanoma (2 papers, 2011 to 2022). A malignant, usually aggressive tumor composed of atypical, neoplastic melanocytes. "In the initial screening of melanoma samples, five genes (USP10, USP11, USP22, USP48 and COPS5) were significantly overexpressed, compared with benign nevi." (PMID 21283576, 2011).
pituitary adenoma (2 papers, 2018 to 2019). "However, neither BRAF V600E nor USP48 M415I/M415V was detected in other types of pituitary adenomas." (PMID 30093687, 2018).
acute promyelocytic leukemia (1 paper, 2019). An aggressive form of acute myeloid leukemia (AML), characterized by arrest of leukocyte differentiation at the promyelocyte stage, due to a specific chromosomal translocation t(15;17) in myeloid cells. "Deubiquitinase USP48 promotes ATRA-induced granulocytic differentiation of acute promyelocytic leukemia cells." (PMID 30898977, 2019).
breast invasive carcinoma (1 paper, 2021). "Additionally, using The Cancer Genome Atlas (TCGA) database, we analyzed the mRNA expression levels of USP48 and Aurora B in breast invasive carcinoma (BRCA), lung adenocarcinoma (LUAD), cervical squamous cell carcinoma (CESC) and prostate adenocarcinoma (PRAD)." (PMID 34445214, 2021).
Cushing syndrome (1 paper, 2023). Cushing's syndrome (CS) encompasses a group of hormonal disorders caused by prolonged and high exposure levels to glucocorticoids that can be of either endogenous (adrenal cortex production) or exogenous (iatrogenic) origin. "Moreover, somatic mutations in the Usp8 and Usp48 genes have frequently been observed in patients with Cushing syndrome, suggesting regulatory roles of these USPs in energy metabolism." (PMID 36834633, 2023). "Moreover, mutations in the Usp8 and Usp48 loci in pituitary tumors cause Cushing syndrome." (PMID 36834633, 2023).
Hepatic steatosis (1 paper, 2022). Steatosis is a term used to denote lipid accumulation within hepatocytes. "CSN-associated DUBs USP15 and USP48 contribute to NF-κB regulation and cylindromatosis (CYLD) is involved in hepatic steatosis." (PMID 35066747, 2022).
leukemia (1 paper, 2025). A malignant (clonal) hematologic disorder, involving hematopoietic stem cells and characterized by the presence of primitive or atypical myeloid or lymphoid cells in the bone marrow and the blood. "Preclinical studies, including USP48 knockout synergizing with hypomethylating agents in leukemia models, provide a rationale for future clinical trials exploring such combinations, though optimal sequencing and toxicity profiles require careful evaluation." (PMID 41209346, 2025).
proliferative diabetic retinopathy (1 paper, 2022). Advanced retinopathy due to diabetes mellitus characterized by the formation of new vessels in the retina. "Finally, USP48 expression has been found altered in pathological eye conditions, such as proliferative diabetic retinopathy." (PMID 36077078, 2022).
renal carcinoma (1 paper, 2025). A carcinoma arising from the epithelium of the renal parenchyma or the renal pelvis. "Furthermore, the identification of USP48 as a stabilizer of oncogenic SIRT6 expands the landscape of druggable deubiquitinating enzymes in renal cancer." (PMID 41354870, 2025).